SOX13 (SRY-box transcription factor 13)
Description:
Transcription factor that binds to DNA at the consensus sequence 5'-AACAAT-3'. Binds to the proximal promoter region of the myelin protein MPZ gene, and may thereby be involved in the differentiation of oligodendroglia in the developing spinal tube (By similarity). Binds to the gene promoter of MBP and acts as a transcriptional repressor (By similarity). Binds to and modifies the activity of TCF7/TCF1, thereby inhibiting transcription and modulates normal gamma-delta T-cell development and differentiation of IL17A expressing gamma-delta T-cells (By similarity). Regulates expression of BLK in the differentiation of IL17A expressing gamma-delta T-cells (By similarity). Promotes brown adipocyte differentiation (By similarity). Inhibitor of WNT signaling.
Synonyms: Sox-13; ICA12; MGC117216
Tractability: PROTAC: ubiquitination databases record sites on it.
Gene: Protein-coding gene on chromosome 1 (204,073,111 to 204,127,743, forward strand). Ensembl gene ENSG00000143842.
Subcellular location: Nucleus; Cytoplasm
Subcellular location (Human Protein Atlas): Nucleoplasm
Pathways (Reactome):
Signal Transduction: Deactivation of the beta-catenin transactivating complex
Gene Ontology:
Molecular function: DNA binding; DNA-binding transcription repressor activity, RNA polymerase II-specific; identical protein binding; protein binding; transcription cis-regulatory region binding; DNA-binding transcription factor activity; DNA-binding transcription factor activity, RNA polymerase II-specific; DNA-binding transcription repressor activity; RNA polymerase II cis-regulatory region sequence-specific DNA binding; sequence-specific DNA binding; RNA polymerase II transcription regulatory region sequence-specific DNA binding
Biological process: negative regulation of canonical Wnt signaling pathway; negative regulation of DNA-templated transcription; negative regulation of transcription by RNA polymerase II; anatomical structure morphogenesis; cell fate commitment; gamma-delta T cell differentiation; positive regulation of brown fat cell differentiation; regulation of DNA-templated transcription; regulation of transcription by RNA polymerase II; spinal cord oligodendrocyte cell differentiation; positive regulation of gamma-delta T cell differentiation
Cellular component: cytoplasm; nucleoplasm; chromatin; nucleus
Genetic constraint (gnomAD): Loss-of-function variants: 26 observed, 57.18 expected, observed/expected ratio (o/e) 0.45, 90% interval 0.33 to 0.63. The upper end of that interval is the gene's LOEUF score, 0.63, which puts it in group 2 of 6, group 1 being the genes least tolerant of losing a copy. Missense variants: 610 observed, 764.12 expected, observed/expected ratio (o/e) 0.8, 90% interval 0.75 to 0.85. Synonymous variants: 306 observed, 303.34 expected, observed/expected ratio (o/e) 1.01, 90% interval 0.92 to 1.11.
Homologues: Orthologues: chimpanzee SOX13 (99% identical), macaque SOX13 (99% identical), pig SOX13 (93% identical), dog SOX13 (92% identical), guinea pig SOX13 (91% identical), mouse Sox13 (89% identical), rabbit SOX13 (88% identical), rat Sox13 (88% identical), zebrafish sox13 (53% identical), tropical clawed frog sox13 (52% identical), Drosophila melanogaster Sox102F (24% identical), Caenorhabditis elegans egl-13 (23% identical), and 3 more. Paralogues in human: SOX5 (46% identical), SOX6 (42% identical), SOX30 (15% identical), SOX9 (13% identical), SOX18 (13% identical), CFAP65 (12% identical), SOX10 (12% identical), SOX17 (12% identical), SOX1 (12% identical), SOX7 (12% identical), SOX11 (12% identical), SOX2 (11% identical), and 8 more.
Diseases named in the same sentence as SOX13 in open-access papers:
SOX13 is named in the same sentence as 46 diseases in open-access papers, as found by Europe PMC text mining. Sharing a sentence is not in itself a finding about the gene and the disease. The quoted sentences say what the papers report.
glioma (17 papers, 2013 to 2025). A benign or malignant brain and spinal cord tumor that arises from glial cells (astrocytes, oligodendrocytes, ependymal cells). "Circ_002136 can bind to a RBP, FUS, and this regulates angiogenesis via the miR-138-5p/SOX13 axis in glioma." (PMID 32894165, 2020). "SOX13 is a target gene of let-7i in colorectal cancer and miR-138-5p circ_002136-mediated glioma angiogenesis." (PMID 33424970, 2020). "As a target gene of miR-138-5p, SOX13 was overexpressed in GECs and was proved to be involved in circ_002136 and miR-138-5p-mediated angiogenesis in gliomas." (PMID 30736838, 2019). "Our data suggests that the feedback loop of FUS/circ_002136/miR-138-5p/SOX13 played a crucial role in the regulation of angiogenesis in glioma." (PMID 30736838, 2019). "FUS bound to circ_002136, while circ_002136 acted as a molecular sponge for miR-138-5p, which had a negative regulatory effect on SOX13 and regulated glioma angiogenesis." (PMID 30736838, 2019). "SOX-13 also showed to improve tube formation of glioma-exposed ECs." (PMID 40640841, 2025). "Similarly, in the same in vitro model, circ002136 sustained glioma angiogenesis by regulating SOX13 (SRY-box transcription factor 13) through inhibition of miR-138-5p." (PMID 35269953, 2022). "SOX13 promoted FUS transcription to form a feedback loop that regulated glioma angiogenesis." (PMID 34116651, 2021). "More importantly, SOX13 could enhance FUS transcription via promoter region, uncovering angiogenesis regulation mediated by the feedback loop of FUS/circ_002136/miR-138-5p/SOX13 in glioma." (PMID 32061256, 2020). "This study further investigated whether SOX13 is involved in the regulatory network of circ_002136 and miR-138-5p in glioma angiogenesis." (PMID 30736838, 2019). "Silencing of cZNF292, circ‐DICER1, and circ_002136 downregulated glioma tube formation through angiogenesis corresponding genes consisting of EGFR, VEGFRs, SOX13, and ZIC4 in human gliomas." (PMID 37953502, 2024). "The promoted SOX13 activated the upstream promoter FUS, forming a positive feedback loop to amplify its effect to regulate angiogenesis in glioma." (PMID 32518520, 2020). "SOX13 bound to the FUS promoter region to up-regulate the expression of FUS, forming a positive feedback loop that promoted glioma angiogenesis." (PMID 30736838, 2019). "SOX13 is a member of the SRY-related high-mobility group box (Sox) transcription factor family and is known to be involved in the progression of several tumors including glioma." (PMID 33652661, 2021). "SRY-Box 13 (SOX13), a member of the Sry-related high-mobility group box (Sox) transcription factor family, was testified to participate in the progression of several tumors, such as glioma and gastric carcinoma." (PMID 31953613, 2020). "FUS/circ_002136/miR-138-5p/SOX13/SPON2 may aid in slowing the gliomagenesis in patients and provide an alternative strategy for glioma treatment." (PMID 30736838, 2019).
colorectal cancer (9 papers, 2019 to 2025). A primary or metastatic malignant neoplasm that affects the colon or rectum. "Emerging evidences revealed that SOX13 is intricately linked to multiple cancers, namely, hepatocellular carcinoma, colorectal cancer, gastric cancer, and gliomas." (PMID 39726600, 2024). "SOX13 promotes colorectal cancer metastasis by transactivating SNAI2 and c-MET and regulates cancer stem-like properties and tumorigenicity in hepatocellular carcinoma cells." (PMID 35631574, 2022). "Studies have found that SOX13 can promote colorectal cancer metastasis by activating SNAI2 and c-MET." (PMID 34122521, 2021). "Previous studies have confirmed that SOX13 is up-regulated in tumors such as renal clear cell carcinoma and colorectal cancer." (PMID 30736838, 2019). "SOX13 is upregulated in tumours such as renal clear cell carcinoma and colorectal cancer." (PMID 33424970, 2020). "SOX13 is induced by hepatocyte growth factor through the JAK2/STAT3 signaling pathway, promoting metastasis in colorectal cancer by upregulating SNAI2 and c-MET expression." (PMID 39726600, 2024). "Additionally, SOX13 as a part of SOX family has been found to be involved in diverse cancers, such as colorectal cancer, Pancreatic Cancer and gastric carcinoma." (PMID 35611828, 2022).
hepatocellular carcinoma (6 papers, 2021 to 2023). A malignant tumor that arises from hepatocytes. "Recent evidence demonstrated that Sox13 maintained stem-like properties in hepatocellular carcinoma." (PMID 37149693, 2023). "SOX13 supports stem-like properties in hepatocellular carcinoma, contributing to increased self-renewal, resistance to chemotherapy, and tumorgenicity." (PMID 38132479, 2023). "SOX13 overexpression in hepatocellular carcinoma activates TWIST1, a major transcription factor in embryonic development, promoting cancer metastasis." (PMID 38132479, 2023). "In hepatocellular carcinoma, SOX13 promotes cell invasion, migration, and epithelial-to-mesenchymal transition through activating Twist1 transcription." (PMID 33613102, 2021). "In mice with hepatocellular carcinoma (HCC), gut microbiota-derived SCFAs, especially acetate, reduce SOX13 expression by inhibiting the activity of histone deacetylases." (PMID 37318214, 2023). "Recent observation showed that Sox13 regulated cancer stem-like properties in hepatocellular carcinoma cells but the mechanism was not clear." (PMID 37149693, 2023).
gastric cancer (5 papers, 2020 to 2025). A primary or metastatic malignant neoplasm involving the stomach. "further revealed that SOX13 contributes to ferroptosis resistance, leading to therapy resistance in gastric cancer." (PMID 40159622, 2025). "We demonstrate that targeting SOX13/SCAF1 inhibits respiratory chain supercomplexes (SCs) assembly to overcome ferroptosis-mediated anticancer therapy resistance in gastric cancer." (PMID 38769295, 2024). "Here, the authors demonstrate that SOX13 promotes ferroptosis-resistance via transactivation of SCAF1, identifying SOX13 as a targeted therapeutic vulnerability in gastric cancer." (PMID 38769295, 2024).
multiple myeloma (5 papers, 2020 to 2024). "LncRNA MALAT1 facilitated the tumorigenesis, invasion and glycolysis of multiple myeloma via miR‐1271‐5p/SOX13 axis." (PMID 32515146, 2020). "Given that SOX13 promotes glycolysis in multiple myeloma and that glycolysis effectively affects breast cancer growth, this work investigated whether SOX13 regulates glycolysis in breast cancer cells." (PMID 35611828, 2022). "Furthermore, it was reported that MALAT1 sponges miR-1271-5p and facilitates multiple myeloma and ovarian cancer progression by regulating SOX13 and E2F5, respectively." (PMID 35320950, 2022).
breast carcinoma (4 papers, 2022 to 2025). "Nonetheless, the biological and clinical implications of SOX13 in human breast cancer (BC) remain rarely known." (PMID 38707897, 2024). "First, the protein level of SOX13 in breast cancer and para-carcinoma tissues was measured, and the data illustrated that SOX13 expression was higher in tumor tissues than in para-carcinoma samples (n = 50, ***p < 0.001)." (PMID 35611828, 2022). "In summary, this investigation revealed the increased expression and tumor-stimulative effect of SOX13 on breast cancer progress." (PMID 35611828, 2022). "This study discovered that SOX13 was upregulated in breast cancer tissues and cells compared with normal sample." (PMID 35611828, 2022). "TRIM11 was proved to be closely related with breast cancer, and SOX13 was proved to affect various cancers by regulating Wnt/β-catenin pathway." (PMID 35611828, 2022). "Taken together, these findings indicated that SOX13 effectively facilitated glycolysis in breast cancer cells." (PMID 35611828, 2022). "In our present study, SOX13 protein level was measured by using western blot assay in tissues and cells, and the results showed that SOX13 was upregulated in breast cancer tissues and cells compared with normal samples." (PMID 35611828, 2022). "In conclusion, this study for the first time revealed that SOX13 promoted breast cancer progression by accelerating TRIM11/Wnt/β-catenin network-mediated glycolysis." (PMID 35611828, 2022). "In the present study, we systemically summarized that SOX13 promoted glycolysis and viability of breast cancer cells by activating TRIM11-mediated Wnt/β-catenin signaling pathway." (PMID 35611828, 2022). "In conclusion, our investigation illustrated that SOX13 facilitated breast cancer cell proliferation and glycolysis by modulating Wnt/β-catenin signaling pathway affected via TRIM11." (PMID 35611828, 2022). "Subsequently, we explored the potential mechanisms of SOX13 in breast carcinogenesis, and we found that silencing SOX13 significantly inhibited glycolysis, whereas overexpressing SOX13 accelerated the glycolysis of breast cancer cells." (PMID 35611828, 2022). "In this study, we assumed that SOX13 exerted crucial roles in breast cancer progression and aimed to verify this hypothesis." (PMID 35611828, 2022). "Therefore, we assumed that SOX13 affected breast cancer and glycolysis by mediating TRIM11/Wnt/β-catenin pathway." (PMID 35611828, 2022). "Nevertheless, the detailed effects of SOX13 on breast cancer are still uncovered." (PMID 35611828, 2022). "Therefore, this work aimed to verify the essential roles of SOX13 in breast cancer progress and to explore the molecular mechanism of SOX13." (PMID 35611828, 2022). "Moreover, silencing SOX13 inhibited breast cancer cell viability, arrested cell cycle at G1/S phase and suppressed glycolysis, while overexpression of SOX13 reversed these events." (PMID 35611828, 2022). "Thus, SOX13 promoted breast cancer cells proliferation by accelerating G1/S transition of MDA-MB-231." (PMID 35611828, 2022). "Here, we hypothesized that SOX13 is closely related to the development of breast cancer." (PMID 35611828, 2022).
pancreatic cancers (4 papers, 2020 to 2024). "Associations between SOX13 and poor prognosis have been observed in various cancer types, including liver cancer, gastric, nonsmall-cell lung cancer, and pancreatic cancers." (PMID 39726600, 2024). "RNAi knockdown of SOX13 reduced the invasion and colony formation ability of pancreatic cancer cells." (PMID 33424970, 2020). "In conclusion, downregulation of let-7c and overexpression of SOX13 play a role in pancreatic cancer." (PMID 33424970, 2020). "Additionally, research has shown high expression of SOX13 in various tumors including gastric, breast, and pancreatic cancers." (PMID 39726600, 2024). "We found that SOX13 (SRY-related high mobility group box transcription factor 13) remained significantly upregulated in PDAC tumours compared with normal pancreas tissue in the pancreatic cancer cohort of TCGA and in an independent data set and was significantly associated with poorer survival." (PMID 33424970, 2020). "Similarly, SRY-box transcription factor 13 (SOX13) and RANBP2-type and C3HC4-type zinc finger containing 1 (RBCK1) enhance resistance to ferroptosis in gastric and pancreatic cancers by boosting mitochondrial respiration." (PMID 39624080, 2024).
diabetes (3 papers, 2008 to 2020). "The dysregulation in the function of SoxD proteins (i.e. Sox5, Sox6, Sox13, and Sox23) have been implicated in different disease conditions such as chondrodysplasia, cancer, diabetes, hypertension, autoimmune diseases, osteoarthritis among others." (PMID 33230925, 2020). "Sox13, a member of the SoxD group, has been identified as a diabetes autoantigen expressed in pancreatic beta-cells and recently as a positive regulator of gamma-delta T cells." (PMID 18565209, 2008). "Challenges may exist to unravel the complex role of SOX13, diabetes, and cancer as SOX13 has been shown to be a nonspecific marker of pancreas tissue damage associated with chronic hyperglycaemia." (PMID 33424970, 2020).
glioblastoma (3 papers, 2012 to 2025). The most malignant astrocytic tumor (WHO grade IV). "For example, circPTN sponges miR-145-5p/miR-330-5p to promote proliferation and stemness in glioblastoma; FUS/circ_002136/miR-138-5p/SOX13 feedback loop regulates angiogenesis in glioblastoma." (PMID 32308563, 2020). "In human glioblastoma, IL-6 levels are endogenously lower in patients who achieve histological or radiographic responses to ICI, and ICI-resistant glioblastoma has elevated stem cell markers (SOX2, SOX4, SOX13, PTPRZ1), which can be driven by IL-621,58." (PMID 40161763, 2025).
type-1 diabetes (3 papers, 2014 to 2022). "Last, a few reports have implicated autoantibodies to sex related Y HMG box (SOX) proteins in type I diabetes and anti-SOX13 in primary biliary cirrhosis, autoimmune hepatitis, and other diseases." (PMID 24804269, 2014). "SOX13 is also known as islet cell antibody 12 (ICA12), as it is a type-1 diabetes autoantigen." (PMID 36247423, 2022). "Additionally, the localization of SOX13 staining in islet cells should be explored further, particularly, as SOX13 is a type-1 diabetes autoantigen (also known as islet cell antibody 12)." (PMID 33424970, 2020). "In this latter study, anti-SOX13 was detected in 18% of patients with PBC, 13% with autoimmune hepatitis, and 18% with type 1 diabetes, at lower frequencies in other conditions including the multisystem autoimmune diseases, SLE, and rheumatoid arthritis, but in only 1% of normal sera." (PMID 24804269, 2014).
autoimmune hepatitis (2 papers, 2014 to 2023). Hepatitis caused by autoantibodies. "simultaneously tested 297 cases of primary biliary sclerosis (PBC), 22 cases of autoimmune cholangitis, 29 cases of autoimmune hepatitis, and 90 patients with T1DM for SOX13-Ab and found a high rate of positivity." (PMID 37138862, 2023).
dermatitis (2 papers, 2020). An inflammatory process affecting the skin. "Igfbp3 and Mir-17hg (Mir-17–92) have been shown to be associated with skin inflammations and their expression was initially decreased in Sox13-/- basal keratinocytes, but this pattern was flipped at 7wk." (PMID 32065580, 2020). "Significant expansion of αβ T cells in the skin of Sox13-/- mice was evident starting ~3 months of age, prior to any visible skin inflammation." (PMID 32065580, 2020). "For this we undertook a whole transcriptome analysis of basal CD49f+ (Itga6) keratinocytes of Sox13-/- mice at 3 and 7 weeks (wks), well before the onset of aberrant skin inflammation starting in ~3 months old (mo) mice." (PMID 32065580, 2020).
thyroid cancer (2 papers, 2024 to 2025). "In addition, upregulated SOX13 gene mutation were evident in thyroid cancer." (PMID 39726600, 2024). "Nevertheless, the functional and clinical significance of SOX13 in human thyroid cancer (THCA) remain largely unelucidated." (PMID 39726600, 2024). "Hence, SOX13 has great promise as a bioindicator for both thyroid cancer prognosis and immune cell invasion." (PMID 39726600, 2024). "Higher SOX13 levels in Thyroid cancer cells may lead to reduced proliferation, migration, and metastasis by regulating ferroptosis." (PMID 39726600, 2024). "However, whether SOX13 is involved in the regulation of thyroid cancer remains unexplored." (PMID 39726600, 2024).
atherosclerosis (1 paper, 2022). A disease characterized by the build-up of fatty material and calcium deposition in the arterial wall resulting in partial or complete occlusion of the arterial lumen. "To predict the role of SOX13 and its target genes in endothelial function and atherosclerosis, we conducted a gene ontology (GO) analysis using the commonly regulated gene lists." (PMID 36247423, 2022). "Dysregulation of SOX13 is involved in cancer development, but its role in atherosclerosis and flow-dependent function in adult ECs was unknown." (PMID 36247423, 2022). "SOX13 flow sensitivity has not previously been reported, nor has a role in atherosclerosis emerged." (PMID 36247423, 2022).